ANGPT2 (angiopoietin 2)
Diseases named in the same sentence as ANGPT2 in open-access papers (continued):
Sharing a sentence is not in itself a finding about the gene and the disease.
ischemic stroke (10 papers, 2013 to 2025). A stroke disorder caused by obstruction of blood flow to the brain, due to thrombotic (local blood clot formation) or embolic (due to a blood clot or other material traveling from another site) event. "We identified the elevation of angiopoietin-2 and leptin receptor as potential novel biomarkers for early detection of ischemic stroke." (PMID 37533068, 2023). "More importantly, we have identified some novel biomarkers, including angiopoietin-2 (Angpt2) and leptin receptor (Lepr), for the detection of ischemic stroke." (PMID 37533068, 2023). "Angpt2 and Vegfa were found to increase cerebrovascular permeability in the early phase of ischemic stroke, which is one of the most important factors for the development of brain edema and finally brings about cell death." (PMID 26030758, 2015). "Angpt2 and Vegfa played an important role in improving angiogenesis and neurogenesis which was favorable for ischemic stroke recovery." (PMID 26030758, 2015). "On the other hand, our result suggested that Angpt2 could be a novel biomarker for the early detection of ischemic stroke." (PMID 37533068, 2023). "In conclusion, our study discovered novel biomarkers, such as Angpt2 and Lepr, that could be used for the early detection of ischemic stroke." (PMID 37533068, 2023). "Therefore, the aim of this study was to evaluate whether the protective effect of Angpt2 against ischemic stroke correlates with enhanced angiogenesis by utilizing the length and area of CD34+ blood vessels as the deciding references for angiogenic activities after cerebral ischemia." (PMID 36358355, 2022). "We previously demonstrated that HUMSC transplantation treated ischemic stroke in rats primarily through the cytokines secreted by the HUMSCs, such as NAP-2, angiopoietin-2, BDNF, CXCL-16, and PDGF-AA." (PMID 31588241, 2019). "Because ANGPT2 regulates angiogenesis through TEK and integrin signaling, and promotes neuroprotection in a model of ischemic stroke, the ANGPT2–TEK/ITGA5:ITGB1 signaling axis from EC:Exc3/Exc5 to fibroblasts (EC:Fib) likely represents a resilience-linked angiogenic support mechanism." (PMID 41035073, 2025).
osteosarcoma (10 papers, 2012 to 2021). A usually aggressive malignant bone-forming mesenchymal neoplasm, predominantly affecting adolescents and young adults. "Among the other detected proteins, angiopoietin-2 expression was previously found to be correlated with tumor stage in osteosarcoma and coagulation factor III (TF3) has been associated with survival and the regulation of tumor progression." (PMID 31195680, 2019). "Another report has shown that miR-543/Angpt2 axis is involved in osteosarcoma metastasis and angiogenesis mediated by CTGF." (PMID 34409031, 2021). "In primary lesion of human osteosarcoma, angiopoietin 2 expression is increased, and this has been reported to be correlated with progression of cancer via promoting distant metastasis." (PMID 31003401, 2019). "In osteosarcoma, the expression of miRNA-543 was inhibited by connective tissue growth factor (CTGF), which resulted in increased Angiopoietin-2 levels that induced osteosarcoma angiogenesis." (PMID 29383201, 2017). "Moreover, in osteosarcoma cell lines (MG63, 143B), the increased expression levels of angiopoietin 2, which is a regulator of angiogenesis as well as VEGF-A, have been shown to be triggered by a decrease in miR-543 expression." (PMID 31003401, 2019). "In accordance with the results from the PCR the quantity of angiogenesis relevant factors including VEGF, ANGPT-1, ANGPT-2 and SDF-1 involved in cell recruitment and osteosarcoma progression in supernatant was measured by ELISA to gain insight on the effects of fucoidan on the protein level." (PMID 28632184, 2017).
diabetic retinopathy (9 papers, 2016 to 2025). "The rs2442598A allele in the ANGPT-2 gene is associated with an increased risk for diabetic retinopathy in Brazilian patients with type 1 DM." (PMID 38792322, 2024). "In diabetic retinopathy, expression of Angiopoietin-2 (Ang-2) is upregulated, which antagonizes Tie2 activation and leads to vascular destabilization." (PMID 41093907, 2025). "ANGPT-2 levels were raised in the vitreous humour in patients with diabetic retinopathy (DR) and were chronically elevated in a rodent model of DR." (PMID 38182581, 2024). "Angiopoietin-2 showed positive significant correlation with albumin (p=0.008) and glycated albumin (p=0.005) in diabetic retinopathy group (Table-III)." (PMID 36415281, 2022). "The significant positive correlation of glycated albumin and angiopoietin-2 in individuals with diabetic retinopathy suggests an interrelated pathway in the genesis and progression of the disease." (PMID 36415281, 2022). "As studies have reported the involvement of angiopoietin-2 (ANGPT-2) in the pathogenesis of diabetic retinopathy (DR), the aim of this study was to investigate the association between the ANGPT-2 rs2442598 polymorphism and DR." (PMID 34762787, 2021). "Moreover, the levels of Angiopoietin-2, a major player in the progression of diabetic retinopathy, were elevated in OIR tissues and consistently downregulated by Aflibercept." (PMID 34321516, 2021). "Notably, diabetic retinopathy is phenocopied by retinal ANGPT2 overexpression, whilst ANGPT1 overexpression can retard the development of diabetic retinopathy and nephropathy." (PMID 34460911, 2021). "The median IQR of angiopoietin-2 in diabetic retinopathy group and in diabetics without diabetic retinopathy groups was 5.70 (5.47-5.80) ng/ml and 5.40 (4.97-5.60) respectively (p=0.033, Table-II)." (PMID 36415281, 2022). "The angiopoietin-2 median IQR in diabetic retinopathy group 5.70 (5.47-5.80) was significantly different (p=0.033) from diabetics without diabetic retinopathy groups 5.40 (4.97-5.60)." (PMID 36415281, 2022).
lung injury (9 papers, 2017 to 2026). "Two variants of the ANGPT2 gene, rs1868554 and rs2442598, were significantly associated with acute lung injury at the IInd clinical stage." (PMID 40115011, 2025). "The decline in ANGPT-1 and increase in ANGPT-2 correspond with marked blood-brain barrier breakdown after brain injury." (PMID 30086801, 2018). "It was found that two SNPs in ANGPT2 (rs1868554 and rs2442598) were significantly associated with higher Ang-2 levels and acute lung injury (ALI) morbidity in trauma patients." (PMID 28824814, 2017).
ovarian carcinoma (9 papers, 2014 to 2024). A malignant neoplasm originating from the surface ovarian epithelium. "An in vitro analysis in an ovarian cancer cell line found that angiopoietin-2 can stimulate the accumulation of CAFs." (PMID 39511039, 2024). "For example, our prior studies indicate that in epithelial ovarian cancer, Tie2+TAMs recruited to tumor ascites by Angiopoietin-2 (Ang2) enhance endothelial function and tumor angiogenesis via IGF1-induced signaling." (PMID 38185636, 2024). "VEGF derived from ovarian cancer cells increases the regulation of angiopoietin 2 in host endothelial cells and induces paracrine remodeling of the host blood vessels to support angiogenesis during tumor growth." (PMID 33639643, 2021). "Overall survival (%) and hazard ratios (HR) of angiopoietin-2, Tie-1 and Tie-2 expressions of ovarian cancer patients." (PMID 33151982, 2020). "The angiogenic factor, angiopoietin-2, and its receptor Tie-2 seem to be significant prognostic factors in primary epithelial ovarian cancer." (PMID 33151982, 2020). "It has been reported that ginsenosides Rg3 can block the occurrence of EMT in ovarian cancer cells by targeting miR-145, which has been shown to play an important role in inhibiting the migration and invasion of BC cells by directly targeting the angiopoietin 2 gene (ANGPT2) of BC cells." (PMID 36278171, 2022). "Angpt2, which we found to be upregulated in FOXC2-expressing mouse ovarian cancer cell lines, has been previously identified as a mediator of tumor angiogenesis." (PMID 36230774, 2022). "The upregulation of ANGPT found in our RNASeq analysis is consistent with studies using mouse models wherein an increased expression of angiopoietins (ANGPT1, ANGPT2, and ANGPT4 and TIE2 (angiopoietin receptor) have been shown to promote ovarian cancer progression." (PMID 35052372, 2021).
pancreatic cancer (9 papers, 2016 to 2022). "MiR-145-5p was found to inhibit the growth of pancreatic cancer and angiogenesis in vivo by suppressing angiopoietin-2, a critical regulator of tumor angiogenesis and progression." (PMID 32082362, 2019). "Intratumoral delivery of miR-145 inhibited the growth of pancreatic cancer xenografts and angiogenesis in vivo, and also suppressed the expression level of angiopoietin-2 protein." (PMID 27570490, 2016). "In pancreatic cancer, angiopoietin-2 drives lymphatic metastasis." (PMID 27353038, 2016).
coronary artery disease (8 papers, 2016 to 2023). "In addition, hypoxia-induced HIF-1 increase in patients with ischemic heart disease promotes the gene transcription of angiogenic factors (including VEGF and Angpt2), which further causes vascular remodeling." (PMID 36600948, 2022). "Circulating Angpt2, not Angpt1 level was positively correlated with coronary artery disease and peripheral artery disease scores in dialysis and transplant patients." (PMID 27991547, 2016).
esophageal cancer (8 papers, 2015 to 2026). A primary or metastatic malignant neoplasm involving the esophagus. "Expression levels of most angiogenic factors in AEG and SCC were similar, biological differences of these two entities of esophageal cancer with respect to angiogenesis are indicated by the different expression of Angiopoietin-2 and Follistatin." (PMID 25885021, 2015). "Of the angiogenic factors VEGF, Angiopoietin-2, PECAM-1, Follistatin, Leptin, G-CSF, HGF, PDGF-BB and IL-8, two angiogenic factors (HGF and Follistatin) are associated with esophageal cancer patients’ prognosis in posttherapeutic tumor tissue." (PMID 25885021, 2015). "In this study, we found that ANGPT2 was correlated with poor prognosis in esophageal cancer." (PMID 36569220, 2022). "Next, we analyzed the expression of these four important genes (VCAN, ANGPT2, MS4A4A, and FOS) between esophageal cancer and normal esophageal tissues." (PMID 36569220, 2022). "In the total 182 hub genes, four hub genes including ANGPT2, VCAN, MS4A4A, and FOS had significant prognostic value in esophageal cancer." (PMID 36569220, 2022). "Four genes including ANGPT2, VCAN, MS4A4A, and FOS were considered to have significant prognostic value in esophageal cancer." (PMID 36569220, 2022). "We found that compared with normal human esophageal tissues, ANGPT2, VCAN, and FOS were significantly upregulated in esophageal cancer tissues, MS4A4A was significantly downregulated in esophageal cancer." (PMID 36569220, 2022). "High levels of ANGPT2, FOS, and MS4A4A were correlated with poor prognosis of esophageal cancer, while high levels of VCAN were correlated with better prognosis of esophageal cancer." (PMID 36569220, 2022). "Among 182 genes, four genes including ANGPT2, VCAN, MS4A4A, and FOS had significant prognostic value in esophageal cancer." (PMID 36569220, 2022). "High levels of ANGPT2, FOS, and MS4A4A were correlated with poor prognosis of esophageal cancer, while high level of VCAN was correlated with better prognosis of esophageal cancer." (PMID 36569220, 2022). "Thus, we considered that hub genes including ANGPT2, VCAN, MS4A4A, and FOS were involved in the pathogenesis of esophageal cancer." (PMID 36569220, 2022).
glaucoma (8 papers, 2019 to 2025). Increased pressure in the eyeball due to obstruction of the outflow of aqueous humor. "Meanwhile, Tie2-activating antibody (ABTAA) rescues the phenotype of glaucoma in double Angpt1/Angpt2-deficient mice, raising the possibility that this signaling pathway could be an interesting therapeutic target for the treatment of glaucoma." (PMID 37091974, 2023). "Tyr and Angpt2 candidate genes have strong literature support for their role in human glaucoma-related conditions." (PMID 36793389, 2022). "Angpt2 is located outside of the high-LD interval, however it contains a cis-eQTL, and is supported by human GWAS studies of glaucoma." (PMID 36793389, 2022). "Our study clearly indicates that germline Angpt2 deletion alone is sufficient to cause defects in the SC in mice, an observation that goes hand in hand with GWAS reports associating ANGPT2 genetic variants with patients who have increased IOP and glaucoma." (PMID 36190459, 2022). "In recent GWAS analyses, ANGPT2 has been identified as a risk locus associated with glaucoma, but the importance of Angpt2 for the SC has not been unanimously shown, and no congenital Angpt2 deletion model has been used in any of the previous mouse studies." (PMID 36190459, 2022). "ANGPT2 functions to influence vascular modeling and, at least in mammals, may impact development of the aqueous humor outflow pathway; thus, NPNT may point toward a mechanism underlying the link between myopia and glaucoma." (PMID 39028695, 2024). "Despite the reduction in SC area, aged Angpt2+/−;Angpt4−/− mice did not display major signs of glaucoma, possibly owing to their less convoluted and thus less obstructive SC morphology when compared to full Angpt2 deletion mice." (PMID 36190459, 2022). "Indeed, a recent study has demonstrated the effectiveness of targeting the Angpt-TEK signaling pathway in a mouse model of glaucoma using an antibody which increases the signaling ability of the context-dependent, weak TEK agonist ANGPT2 by clustering it into higher-order multimers." (PMID 31621585, 2019). "Tie2 deletion as well as Angpt1;Angpt2 double deletion in mice lead to complete absence of SC, highly elevated IOP, and severe glaucoma." (PMID 36190459, 2022).
ischemia (8 papers, 2013 to 2025). A hypoperfusion of the BLOOD through an organ or tissue caused by a PATHOLOGIC CONSTRICTION or obstruction of its BLOOD VESSELS, or an absence of BLOOD CIRCULATION. "The pigment epithelium-derived factor, another angiogenic factor, modulates BBB permeability and attenuates lesion volume expansion at an acute phase of ischemia; intriguingly, Angiopoietin 2 (Angpt2) has been observed to have a similar effect." (PMID 36358355, 2022). "Only angiogenin and angiopoietin-2 were increased in MI patients compared to GBM patients, suggestive of their association with the acute onset of ischemia occurring in MI." (PMID 31428150, 2019). "Before endothelial proliferation begins, most of the well-known angiogenic factors including VEFG and angiopoietin-2 show increased expression as early as a few hours after ischemia." (PMID 26637168, 2015). "The present protein analyses and results strongly support the hypothesis that catalpol exerts its anti-inflammatory, antioxidative, and anti-ischemic/hypoxic properties via mechanisms of downregulating the ischemia-associated overexpression of MCP-1, β-catenin, HIF-1α, VEGF, and angiopoietin-2." (PMID 40362263, 2025). "When contrasted with DKK1 or Lucentis, catalpol exhibited similar protective effects against retinal ischemia via significantly (p < 0.05) blunting the ischemia-induced overexpression of β-catenin, VEGF, or angiopoietin-2." (PMID 40362263, 2025). "In part, ANGPT2 expression appears to be involved in vascular pruning and maturation, as well as in the resolution of inflammation by reducing VEGF-A expression and reducing MCP-1-induced macrophage migration to the site of ischemia." (PMID 40299401, 2025).
type 2 diabetes (8 papers, 2011 to 2026). "Similarly, urinary ANGPT2 levels are increased in patients with type 2 diabetes with renal damage and are associated with albuminuria." (PMID 27207083, 2016). "Importantly, poor glycaemic control is paralleled by high circulating ANGPT2 levels in patients with type 2 diabetes." (PMID 27207083, 2016).
acute pancreatitis (7 papers, 2016 to 2026). An acute inflammatory process that leads to necrosis of the pancreatic parenchyma. "Although sFlt-1 is most studied as the laboratory marker of preeclampsia, we observed increased serum concentrations of sFlt-1 (together with angiopoietin-2) in acute systemic inflammation associated with severe acute pancreatitis." (PMID 34439802, 2021). "First, heterogeneity of the available data remains a limitation for the development of uniform clinical recommendations for IL-6 and angiopoietin-2 in acute pancreatitis." (PMID 41590239, 2026). "ANGPT2 is an accurate early predictor of acute gastrointestinal injury and intestinal barrier dysfunction in patients with acute pancreatitis." (PMID 38808888, 2024). "In further study the more specific attention should be focused on the correlation between cystatin C and even angiopoietin 2, which appeared to be a relevant predictor of renal dysfunction in acute pancreatitis patients." (PMID 28105442, 2016). "In the present study, we included another laboratory marker associated with endothelial dysfunction, the soluble fms-type tyrosine kinase 1 (sFlt-1), which we have previously shown to correlate with serum angiopoietin-2 and to predict organ failure and coagulopathy in acute pancreatitis." (PMID 34439802, 2021). "One study shows that serum angiopoietin-2 may be a potential predictor of acute pancreatitis severity and an indicator of renal dysfunction in the development of acute pancreatitis-renal syndrome." (PMID 29987200, 2018).
diabetic nephropathy (7 papers, 2014 to 2026). "Studies on diabetic nephropathy indicated that Angpt2 promotes autophagy in MCs through miR‐33‐5p/SOCS5 loop." (PMID 33987885, 2021). "ANGPT2 has been reported to be involved in diabetic nephropathy." (PMID 35468852, 2022). "Most recently, resveratrol has been found to attenuate experimental diabetic nephropathy, related in part to suppression of VEGF and angiopoietin 2 -induced changes in glomerular permeability." (PMID 25133636, 2014).
liver fibrosis (7 papers, 2013 to 2023). "Angiopoietins correlated significantly with hepatic fibrosis; however, only angiopoietin-2 was retained in the final model, which also included age, platelets, AST, INR, and GGT." (PMID 23823085, 2013). "Our novel noninvasive liver fibrosis model, based on serum angiopoietin-2 levels, outperforms other indices and should help substantially in managing CHC and monitoring long-term follow-up prognosis." (PMID 23823085, 2013). "In addition, factors such as low platelet counts, low or high ALT levels, high serum angiopoietin-2 levels, high FIB-4 score, and previous treatment history have also been identified as predictors associated with improved liver fibrosis." (PMID 37013471, 2023). "Another research suggested that HCC cell-derived exosomes promoted the angiogenesis of HUVECs by transmitting angiopoietin-2 (ANGPT2) to HUVECs, which in turn, promoted the progression of liver fibrosis." (PMID 36276639, 2022). "Recent reports suggest that angiopoietin-2 (Ang2) can predict non-regression of liver fibrosis after successful HCV eradication." (PMID 36680221, 2023). "A univariate analysis revealed that baseline liver fibrosis stage (F0–2 vs. 3–4, P = 0.002), FIB-4 index (P = 0.005), angiopoietin-2 (P = 0.004), HCV-RNA (P = 0.025), and AST (P = 0.029) were significantly associated with non-regression at 96 weeks after DAA initiation." (PMID 33911145, 2021).